GFAP (glial fibrillary acidic protein)
Diseases named in the same sentence as GFAP in open-access papers (continued):
Sharing a sentence is not in itself a finding about the gene and the disease.
cancer (continued). "Misinterpretation as carcinoma metastasis was common, since GFAP expression was absent in the primitive neuronal component, whereas TTF-1 expression was detected in 15/19 cases (79%) based on immunohistochemistry." (PMID 39899075, 2025). "GSCs showed characteristics consistent with cancer stem cells: namely, neurosphere formation; expression of stem cell markers Sox2 and OLIG2 and multilineage differentiation with markers for astrocytes (GFAP), neurons (MAP2) or oligodendrocytes (O4)." (PMID 37997289, 2024). "Key genes that contribute to gliogenesis but also contribute to the stemness in GBM: Notch (cancer stem cells), Sox9, Sox4, and SHH.Notch signaling pathway: In gliogenesis, Notch effector protein (NIFA) binds to GFAP promotor and contributes to astrocytogenesis." (PMID 35538578, 2022). "The anti-glial fibrillary acidic protein (GFAP) antibody was used as a marker of glial cells (mouse glial cells and U87 cells), the anti-neuronal nuclei (NeuN) to mark the neurons, and the human anti-CD44 was used as a cancer cell marker." (PMID 34069377, 2021). "However, it has been reported that paclitaxel can change intermediate filaments including GFAP in various cells and can induce the activation of JNK pathway leading to the apoptosis of carcinoma cells." (PMID 31707979, 2019). "Three non-cancer healthy control individuals who did not receive the survivin immunogen were also assessed for survivin and GFAP expression on CD9+ exosomes (bottom row)." (PMID 29383115, 2017). "Immunofluorescence staining for nestin but not GFAP and β-tubulin was observed in the cancer stem cells, which contrasts with the results observed in cancer cells." (PMID 28955297, 2017). "As opposed to most carcinomas, staining for cytokeratin is rarely positive, and the same applies to GFAP." (PMID 28953948, 2017). "Moreover, the CD133+ cells showed characteristics consistent with CSC, namely neurospheres formation, expression of neural/cancer stem cell markers (CD133, Nestin, SOX-2) and differentiation marker (GFAP)." (PMID 24978848, 2014). "Lack of GFAP expression and nuclear positivity for TTF1 are common in embryonal components which may cause misinterpretation as carcinoma although these tumors do not express cytokeratins." (PMID 33876327, 2021). "GFAP was easily detected by Western Blotting in Panc02, 7265PDA, 6606PDA, 6606l cells and brain, but only elusive expression was observed in 6606PDA cell derived carcinomas by immunohistochemistry (data not shown)." (PMID 25885700, 2015). "Additionally, we found that in the NCP model, palmitoylation of the astrocyte marker protein GFAP is upregulated, promoting the proliferation of glial cells and the inflammatory response and participating in the signaling and maintenance of cancer pain together with microglia (data not shown)." (PMID 38164190, 2024). "The anti-cancer effects of lipid-soluble vitamins in various GBM cell lines are attributed to a diverse range of molecular mechanisms through changes in the expression of a wide range of biomarkers, of which CDK2, GFAP, p27, Bax, and CASP8 genes may have some clinical value." (PMID 35889829, 2022). "Cancer cells were identified as non-hematopoietic (CD45-) and polyploidy of chromosome 8 by FISH.A large strong polyploidy (≥5 copies) chromosome 8+, CD45− CTC was observed, with GFAP negative expressed." (PMID 27517490, 2016). "Briefly, and as illustrated by the GFAP mRNA expression profile, although not the only example, a high COPA score did not necessarily imply a significant outlier expression difference between the normal and cancer groups." (PMID 21365010, 2011).
brain disorder (23 papers, 2009 to 2025). A disease affecting the brain or part of the brain. "The dysfunction of these cells is widely associated with brain disorders, which are often characterized by variations in the astrocyte protein markers GFAP and S100B, in addition to alterations in some of its metabolic functions." (PMID 38535311, 2024). "To choose the concentration of use of the compounds, we first exposed the astrocyte cultures to different concentrations of MG, FC, LPS or STZ and evaluated the level of GFAP and S100B, which are frequently associated with brain disorders." (PMID 38535311, 2024). "In contrast to the neuronal marker MAP2, the astrocytic marker glial fibrillary acidic protein (GFAP) has been linked to several types of brain disorders and injuries." (PMID 39596085, 2024). "NfL, t-tau, and glial fibrillary acidic protein (GFAP) have recently emerged as blood-based biomarkers in brain disorders, of which NfL has been most extensively studied." (PMID 39363047, 2025). "Glial Fibrillary Acidic Protein (GFAP), an emerging fluid biomarker in brain disorders usually employed to identify astrocytic reactivity state, a well-documented process in AD and neurodegeneration, was identified." (PMID 38687811, 2024). "In response to brain disorders, astrocytes change their phenotype to that of reactive astrocytes, which are characterized by increased glial fibrillary acidic protein (GFAP) expression and hypertrophy." (PMID 36899860, 2023). "For example, brain diseases are characterized by the active inflammatory state of the astrocytes, which presents a high expression of the glial fibrillary acidic protein (GFAP), and many other molecular markers." (PMID 36143475, 2022). "Astrocytes become activated with morphological changes and increased expression of glial fibrillary acidic protein (GFAP) during the pathogenesis of brain diseases." (PMID 34336001, 2021). "Brain diseases are characterized by the active inflammatory state of astrocytes, which is usually manifested as up-regulation of GFAP." (PMID 31905673, 2019). "Brain diseases are characterized by the active inflammatory state of the astrocytes, which is usually described as up-regulation of glial fibrillary acidic protein (GFAP)." (PMID 31611796, 2019). "It should be noted that although the percentage of GFAP+ astrocytes significantly decreased after exposure to Chase ABC, many of them showed aberrant morphology similar to those seen after brain disorders." (PMID 19845964, 2009).
psychiatric disorder (21 papers, 2012 to 2025). A disorder characterized by behavioral and/or psychological abnormalities, often accompanied by physical symptoms. "In this study, we evaluated the diagnostic utility of serum NfL and GFAP levels to distinguish sporadic bvFTD from late-onset psychiatric disorders in a large multicentre neuropsychiatric cohort." (PMID 40486666, 2025). "GFAP, or astroglia marker, has been extensively investigated for its level and various isoforms, and it is thought to be a biomarker for neurological and psychiatric disorders." (PMID 39838666, 2025). "Accordingly, the expression of astrocyte-specific markers, such as glial fibrillary acidic protein (GFAP) and Ca2+-binding protein, S100β, has been found altered in this mental illness." (PMID 40650814, 2025). "Reduced astrocyte numbers, morphological atrophy, decreased GFAP expression, as well as inadequate glutamate uptake, are manifestations of cognitive dysfunction in a variety of psychiatric disorders." (PMID 35860850, 2022). "Other reports show a reduction in GFAP levels and decreased glial density in the prefrontal cortex, cortico-limbic areas and amygdala in both the adult brain of patients with psychiatric disorders and mouse models." (PMID 28546341, 2017). "Additionally, GFAP plays a significant role in psychiatric disorders, where its levels often change." (PMID 39796043, 2024). "However, while increased S100B levels in patients with SCZ have been interpreted as a marker of structural damage or, alternatively, as a sign of astroglial dysfunction, the role of GFAP (a classical marker of astrogliosis) in psychiatric disease remains controversial." (PMID 26733814, 2015). "The expressions of GABAARγ2, GAD65, LGI1, SCN1β, and GFAP were significantly higher in the hippocampus of epileptic subjects with psychiatric disorders compared to patients without psychiatric disorders (P ≤ 0.05)." (PMID 37658249, 2024).
retinopathy (16 papers, 2010 to 2025). "The expression and activation of matrix metalloproteinase-9 (MMP-9) has previously been observed in retinopathies, and this effect is directly associated with an increase in GFAP expression." (PMID 28112220, 2017). "Understanding the relationship between GFAP expression and the release of inflammatory mediators is essential for advancing targeted therapeutic strategies for retinal disorders." (PMID 40906190, 2025). "These groups were selected because of the observed decrease in GFAP immunoreactivity in the WT retinas but increased GFAP astrogliosis in the CX3CR1KO retinas in our model of hypoxia-induced retinopathy." (PMID 39940901, 2025). "To investigate the role of astrocytes in hypoxia-induced retinopathy, we utilized a 7-day systemic hypoxia model using the GFAP-CreERT2:Rosa26iDTR transgenic mouse line." (PMID 38785974, 2024). "Regarding inflammation, the glial fibrillary acidic protein (GFAP) is a marker of astrogliosis, a phenomenon that is typically observed in proliferative retinopathies such as DR." (PMID 37887292, 2023). "GFAP is a marker of gliosis and is increased in reactive Müller glia cells in various retinal disorders." (PMID 32714489, 2020). "We conducted IHC and Western blots to study the effect of intravitreal injection of RO4929097 on upregulation of GFAP in NaIO3-induced retinopathy." (PMID 32724452, 2020). "Retinopathy is typically characterized by macroglia activation and gliosis identified by glial fibrillary acidic protein (GFAP) overexpression, which can be considered as a marker for retinal damage." (PMID 32085589, 2020). "As expected, western blotting analysis and immunolabeling with anti-GFAP antibody, revealed an increased expression of GFAP, and consequent gliosis, indicating that, 48 hours after treatment, retinopathy was well established." (PMID 25259650, 2014). "However, GFAP accumulation in Müller cells was reported as an essential photoreceptor stress parameter in retinopathy induced rats, in accordance with our findings." (PMID 33628377, 2021). "The data suggest that human vitreous body GFAP may be an interesting protein biomarker for indirect quantification of the glial response to retinal disorders." (PMID 26279003, 2015). "Interestingly, a previous study showed that intravitreal injection of 2-methoxyestradiol in retinopathy in a premature rat model demonstrated positive GFAP expression in MGCs and negative VEGF immunoreaction in retina." (PMID 28886036, 2017).
peripheral neuropathy (15 papers, 2013 to 2025). A disorder affecting the peripheral nervous system. "TDF administered to wild-type (wt) and GFAP-gp120 transgenic (tg) mice caused peripheral neuropathy, as indicated by nerve conduction slowing and thermal hyperalgesia." (PMID 31748578, 2019). "Based on our study, there is no advantage of combined testing of the two molecules compared to testing GFAP alone in patients with peripheral neuropathies." (PMID 39565457, 2025). "In our study, GFAP levels in CSF showed a strong correlation with the presence of electrophysiologically confirmed axonal damage in patients with peripheral neuropathy." (PMID 39565457, 2025). "Peripheral neuropathy in GFAP astrocytopathy is mostly axonal, predominantly affecting the lower motor extremities." (PMID 39449321, 2024). "Other research studies have also indicated that the major phenotype of GFAP-related peripheral neuropathy primarily manifests as axonal injury, specifically affecting the motor fibers in the lower extremities." (PMID 38585352, 2024). "(v)GFAP in the CSF is a sensitive marker of axonal damage in patients with peripheral neuropathy." (PMID 39565457, 2025). "The rate of peripheral neuropathy in patients with GFAP astrocytopathy ranges from 24% to 31%." (PMID 39449321, 2024). "Secondly, blockade of IL-1R1 with intrathecal administration of the IL-1 receptor antagonist (IL-1ra) during the early phase of peripheral neuropathy increased the expression of both astrocyte P450c17 and GFAP in the spinal cord dorsal horn, and this increase was blocked by IL-1β administration." (PMID 31281242, 2019). "In this study, we set out to determine the usability of serum NfL (sNfL), GFAP (sGFAP), and RNFL as reliable and easily accessible biomarkers of the progression and severity of chronic oxaliplatin-induced peripheral neuropathy (OIPN)." (PMID 32409710, 2020). "We set out to determine the usability of serum neurofilament light chain (sNfL), serum glial fibrillary acidic protein (sGFAP), and retinal parameters by using optical coherence tomography (OCT) as reliable biomarkers of the progression of oxaliplatin-induced peripheral neuropathy (OIPN)." (PMID 32409710, 2020). "Histological and molecular studies showed a significantly increased level of glial fibrillary acidic protein (GFAP) expression in the ACC after peripheral neuropathy, and neither MCS treatment nor ZIP administration affected this increase." (PMID 28801619, 2017).
CNS tumors (14 papers, 2019 to 2026). "GFAP (glial fibrillary acidic protein) is an astrocytic marker frequently used in the histological classification of CNS tumors." (PMID 41311621, 2025). "Further studies, including more cases of the differential diagnoses for CNS tumors with an oligodendrocyte-like pattern, are required to confirm the utility of GFAP immunostaining in this setting." (PMID 35885538, 2022). "This work proposes a novel specific utility interpreting GFAP staining in CNS tumors with predominant oligodendrocyte-like areas." (PMID 35885538, 2022). "Common immunostains that can be used in approaching CNS tumors with an oligodendrocyte-like pattern include IDH, neuronal markers (synaptophysin, neurofilament protein, and NeuN), EMA, and GFAP." (PMID 35885538, 2022). "These cells were composed of hyperchromatic cells forming a rosette-like structure and were immunopositive for GFAP with reduced expression of H3K27me3, which is consistent with the occurrence of a metastatic EPN-PFA (WHO CNS grade 3, based on 5th ed WHO Classification of CNS Tumor, 2021)." (PMID 37046450, 2023).
genetic disorder (10 papers, 2014 to 2025). "This is a primary genetic disorder of astrocyte caused by dominant gain-of-function mutations in the gene coding for an intermediate filament protein glial fibrillary acidic protein (GFAP)." (PMID 38782207, 2024). "Loss of vimentin or desmin leads to mitochondrial dysfunction and increased oxidative stress in various models, worsening the progression of genetic diseases such as those caused by desmin and glial fibrillary acidic protein (GFAP) mutations, which amplify oxidative damage." (PMID 41465278, 2025). "AxD is a primary genetic disorder of astrocyte characterized by the upregulation of GFAP and reactive astrocyte response." (PMID 38782207, 2024). "Recent research has revealed that astrocytes respond to an increased GFAP level after immune system diseases, tumors, trauma, ischemic or infectious or genetic diseases or neurodegenerative insult." (PMID 38216970, 2024).
metabolic disorders (9 papers, 2021 to 2026). "Anti-GFAP staining exhibited that the astrocytes in the demyelinating areas were in metabolic disorder and had several anti-GFAP strong positive substances (weak positive reaction in control dogs) in their cytoplasm." (PMID 34384430, 2021). "GrimAge residuals showed associations with a broad range of blood-based biomarkers implicated in age-related disease and premature mortality risk, including inflammation (CRP, WBC, IL-6, and TNF-α), oxidative stress (GGT), neuropathology (GFAP), and metabolic disease (MetS)." (PMID 36153327, 2022). "In this study, the metabolic disorder of astrocytes in CDV-infected dogs showed a strong positive reaction, but in control dogs, weak positive reactions stained by anti-GFAP immune technique were observed in the white matter, especially in demyelinating areas." (PMID 34384430, 2021).
movement disorder (9 papers, 2018 to 2026). Neurological conditions resulting in abnormal voluntary or involuntary movement, which may impact the speed, fluency, quality and ease of movement. "Because the marker of astrocyte activity is the GFAP gene, an increase in GFAP is associated with an increase in astrocyte activity, so by these results, prolactin may have exerted its protective effects on the improvement of movement disorders by acting on astrocytes in the affected regions." (PMID 35432801, 2021). "At 1 month of age, LO GFAP-Coasy mice showed movement disorders characterized by impaired balance and coordination as measured by the rotarod test and this movement disorder worsened as the mice aged (from month 1 to month 12)." (PMID 39301217, 2024). "According to the results of the present study, in cases with ICH, ICV injection of prolactin increased PRL receptor expression in the affected regions, and increased GFAP and APOE genes expression, and caused improved movement disorders in rats." (PMID 35432801, 2021). "However, we also observed a distinct milder phenotype in LO GFAP-Coasy mice, which does not affect the animals’ life expectancy but is associated with disorganization of the cerebral cortex and cerebellum layers, and severe movement disorders." (PMID 39301217, 2024). "The results of the PRL receptor, GFAP, and APOE gene expression also confirmed the results of improving movement disorders in the behavioral section of the study." (PMID 35432801, 2021).
central nervous system diseases (8 papers, 2013 to 2025). "Research has shown that GFAP is a potential biomarker for brain injury in many central nervous system diseases." (PMID 39911384, 2025). "An abundance of research studies has shown that blood biomarkers, such as NfL and GFAP, are promising indicators for monitoring central nervous system diseases." (PMID 37576000, 2023). "Reactive astroglia are characterized by increased cell size and the production of cytoskeletal intermediate filaments; for this reason, GFAP labeling has been widely used to identify this process in a variety of central nervous system disorders, including TBI." (PMID 35360493, 2022). "Due to these factors, GFAP has received much attention as a proposed biomarker in studies of central nervous system diseases." (PMID 23533492, 2013). "Consequently, Glial Fibrillary Acidic Protein (GFAP) staining has been widely used to identify reactive glia in a variety of central nervous system diseases including TBI." (PMID 35360493, 2022). "Therefore, GFAP has received much attention as a reliable biomarker in studies of central nervous system diseases." (PMID 28468332, 2017).